ICAM1 (intercellular adhesion molecule 1)
Diseases named in the same sentence as ICAM1 in open-access papers (continued):
Sharing a sentence is not in itself a finding about the gene and the disease.
tumor (continued). "However, nobody has investigated yet the role played by ICAM-1 in tumor infiltrating lymphocytes' exit from tumor." (PMID 30258446, 2018). "Additionally, we investigated the immunoreactivity of ICAM1 in normal breast tissue and tumor specimens, in addition to samples from a cohort of TNBC patients." (PMID 30082828, 2018). "Thus, we demonstrate a novel tumor escape suppressing perforin expression in CD8+ T cells mediated by ICAM-1 and TGFβ2, which can be targeted in combination for cancer immunotherapy." (PMID 29966014, 2018). "IL-35 may also induce ICAM1 expression in immune cells or endothelial cells and influence the tumour immune microenvironment." (PMID 28102193, 2017). "ICAM-1 was highly co-expressed in HIF-1α positive areas on the tumor cell surface." (PMID 29228586, 2017). "Some reports suggest that CD11b+ Ly6G+ might accumulate in the liver due to tumor-derived inflammatory factors such as PGE2 of COX-2 origin, VEGF and IL-1β, released by LSECs after interacting with tumor cells via LFA-1/ICAM-1." (PMID 29207960, 2017). "ICAM1 is among the key adhesion molecules known to play an important role in cancer metastases, possibly through colonization, and was suggested to enhance tumor growth being a pro-angiogenic factor." (PMID 28415753, 2017). "ICAM-1 can engage in receptor-ligand binding between a T-cell and an antigen-presenting DC and thereby contribute to T-cell activation as well as recruitment of immune cells from the blood stream to endothelial cells before extravasation to the tumor." (PMID 28638385, 2017). "Finally, we demonstrate that ICAM-1 is expressed in the tumor stroma of human head and neck cancers in correlation with the presence of clusters of invasive cancer cells." (PMID 27901489, 2017). "Moreover, recent studies have indicated that TAMs and tumor-associated neutrophils (TANs) can also contribute to tumor cell egress and survival via NCOA1, CCL18, VCAM1, ICAM1 etc." (PMID 28591712, 2017). "After adhesion, the transmigration of tumor cells across the endothelial layer might be mediated by LFA1/ICAM-1 interaction since the cells partially depleted in β2-integrin showed an impaired capacity of trans-endothelial migration." (PMID 29207960, 2017). "However, in vivo results employing tumor cells transfected with human ICAM-1 suggest that functionally mouse LFA-1 can recognize human ICAM-1." (PMID 29312326, 2017). "Because we consider that the in vitro three-dimensional collagen lattices contraction assay is a powerful tool to unveil new genes or signaling pathways that regulate cell contractility, such a screen was used to disclose a novel role for ICAM-1 during tumor progression." (PMID 27901489, 2017). "Among target genes transcriptionally activated by NF-κB, secretory proteins such as ICAM1 from normal fibroblasts could be highly responsible for constitution of tumor microenvironment." (PMID 28827764, 2017). "Notably, ICAM1 inhibition by shRNA resulted in reduced tumor development and metastasis in mice, thus suggesting ICAM1 a good therapeutic target." (PMID 27738343, 2017). "To test this hypothesis, we quantified the extravasation of non-targeted, single targeted (a-E-selectin) and dual targeted (50/50 of a-E-selectin and a-ICAM-1) liposomes in the bMTM containing a co-culture of MDA-MB-231 tumor cells and HBTAEC." (PMID 28839211, 2017). "Because the need for specific CAF sub-population identification is compelling, detection of ICAM-1 in the tumor stroma, coupled with a specific fibroblast marker might constitute an interesting biomarker for clinical evaluation of tumor stroma proinvasiveness." (PMID 27901489, 2017). "We speculate that TM and at times, F292G CAR T cells reacted with murine ICAM-1 that was upregulated in response to exposure to inflammatory cytokines secreted by CAR T cells or lysed tumor cells during engagement with human ICAM-1-expressing tumors." (PMID 29085043, 2017).
tumor (continued). "To determine whether ICAM-1 is involved in this tumor invasion phenotype, we subjected shICAM-1 #2, and shICAM-1 #4 cells to a transwell invasion assay in vitro." (PMID 29228586, 2017). "We hypothesized that blocking ICAM-1 interferes with macrophage migration to the tumor, thereby prolonging mouse survival." (PMID 29228586, 2017). "Given that the IL-35-induced adhesion to HUVECs is fibrinogen-dependent, we hypothesized that IL-35 promotes tumour–endothelial cell adhesion through an ICAM1–fibrinogen–ICAM1 bridge." (PMID 28102193, 2017). "Tumors with lower ICAM-1 expression had a significantly reduction in tumor size." (PMID 29228586, 2017). "Furthermore, the previous stimulation of tumor cells with soluble ICAM-1 (sICAM-1) increased the activity of ManR on LSECs and further reduced the cytotoxic potential of LSLs once they have interacted with tumor activated LSECs." (PMID 29207960, 2017). "Tumor endothelium, by its unique position, regulates the trafficking of leukocytes into tumors by controlling the expression of adhesion molecules such as intercellular adhesion molecule-1 (ICAM-1) or vascular cell adhesion molecule-1 (VCAM-1)." (PMID 29104248, 2017). "Therefore, we developed an ICAM-1 specific CAR with broad anti-tumor applicability that utilized a reduced affinity targeting strategy to significantly boost efficacy and safety." (PMID 29085043, 2017). "Moreover, CD45- ICAM1+ cells possessed in vitro stem-like properties, as demonstrated by sphere formation and in vivo tumor induction." (PMID 27738343, 2017). "Radiation induces not only direct tumor cell killing but also phenotype alteration of tumor cells, including MHC-I, carcinoembryonic antigen, mucin-1, Fas, and ICAM-1, which may affect tumor immunogenicity." (PMID 28465485, 2017). "This might be related to the activation of an inflammatory microenvironment triggered by tumor LFA-1 with endothelial ICAM-1." (PMID 29207960, 2017). "The recombinant virus used in fowlpox-TRICOM expresses three costimulatory transgenes, B7.1 (CD80), Intercellular Adhesion Molecule 1 (ICAM-1), and lymphocyte function-associated antigen 3 (LFA-3), plus one or more tumor-associated antigens, such as Carcinoembryonic antigen (CEA) and MUC-1." (PMID 27669306, 2016). "From this information, we hypothesize that although poly I:C treatment slightly increased ICAM-1 expression, this stimulation may be insufficient to provide an anti-tumor condition similar to the HVJ-E treatment." (PMID 27259252, 2016). "Remarkably, increased expression of multiple cell surface proteins implicated in homing and cell motility was detected in the tumour cells, including integrins such as LFA-1 (CD11a), VLA-4 (CD49d) and MAC-1 (CD11b), and adhesion molecules such as MadCAM-1, ICAM-1 (CD54) and L-selectin (CD62L)." (PMID 27297662, 2016). "Conversely, it has also been reported that IFN-γ treatment of tumour cells with high basal levels of ICAM-1, such as K562 cells, up-regulates major histocompatibility class I which acts as a ligand for inhibitory receptors on NK cells and reduces NK cytotoxic activity." (PMID 27098723, 2016). "Similarly, Huang and colleagues demonstrated inhibition of TNF-α-induced ICAM-1 expression along with inhibition of tumor cell (A549 cells) invasion and MMP-9 expression." (PMID 26823953, 2016). "Additionally, abnormal expression of adhesion molecules, as ICAM-1, has an integral role in tumor growth, invasion, metastasis, and evasion from the host immune defense." (PMID 27252704, 2016). "The combination of ICAM-1 rs5498 and tumor history predicts the EOC prognosis." (PMID 27252704, 2016). "The adhesion molecules evaluated in this study, namely ICAM-1, VCAM-1 and ALCAM, are known to be involved in tumor cell attachment to the vascular endothelium and are directly implicated in the progression of tumor growth, including early stages of metastasis seeding in the brain." (PMID 26706037, 2016).
tumor (continued). "Our results have shown that the expression of endothelial adhesion molecules as VCAM-1 and ICAM- 1 was notably increased in B16F10-ARF−/− tumor xenografts which may also contribute to macrophages recruitment." (PMID 27572316, 2016). "Consistent with VEGF-stimulation of tumor endothelial cells being associated with lower expression of endothelial activation markers, B16.F10 tumors express higher levels of VEGF and lower levels of endothelial ICAM-1 and VCAM-1 than T241 tumors." (PMID 27385210, 2016). "Yet, miR-222 down-regulates the expression on tumor cell surfaces of intracellular cell adhesion molecule 1 (ICAM-1) whose binding to lymphocyte function-associated antigen (LFA-1) is essential for optimal activation of cytotoxic T cells, which in turn mediate tumor cell lysis." (PMID 25886763, 2015). "Therefore, malignant CNS tumor cells reduce the expression levels of ICAM1 to achieve their tumor immune escape." (PMID 26528477, 2015). "Neutrophils bound tumor cells engaging integrins and inducing ICAM-1 clustering on the tumor cell." (PMID 26819959, 2015). "As a ligand for the leukocyte integrin LFA-1, endocan acts as an inhibitor of LFA-1 / ICAM-1 interaction, an important step in the firm adhesion of leukocytes to the endothelium, and thereby could regulate the leukocyte migration into tumor tissues." (PMID 25575808, 2015). "Tumour cells were shown to be rapidly engrafted into bone marrow endothelial microdomains, where endothelial cells express higher level of adhesion molecules such as E-selectin, P-selectin, and intercellular adhesion molecule (ICAM-1)." (PMID 26480944, 2015). "However, Ki67-positive cells were poorly detected within ICAM1-positive areas within tumor tissues, suggesting that ICAM1 indirectly contributes to tumor growth possibly by enhancing the viability of cells." (PMID 25879517, 2015). "Our findings, together with previous studies, suggest that ICAM-1 is in large part responsible for the suppressed tumor metastasis and decreasing M2-like macrophage presence via abrogation of efferocytosis of apoptotic tumor cells." (PMID 26068788, 2015). "In conclusion, we report a novel mechanism by which ICAM-1 in the tumor microenvironment, via restraining efferocytosis of apoptotic tumor cells, can block M2 macrophage polarization through regulation of PI3K/AKT activation, which leads to prevention of tumor metastasis." (PMID 26068788, 2015). "Furthermore, ICAM-1 expression correlated with increased macrophage infiltration within the SCC tumor." (PMID 26231039, 2015). "Finally, percent of samples with > 50% of tumor cells expressing ICAM1 was 43% and 20% for CB and NB, respectively." (PMID 26338962, 2015). "Further study of the relationship between ICAM-1 induction and stimulation of anti-apoptosis signaling pathways will lead to greater understanding of the survival mechanisms employed by cancer cells in hypoxic tumor microenvironments." (PMID 26484240, 2015). "In addition, higher dose of ICAM1 knockdown CE146T cells are needed to induce tumor formation, revealing that ICAM1 knockdown reduces in vivo tumorigenic potential, one of the important properties of CSC." (PMID 26571024, 2015). "Furthermore, silencing E2F1 increases ICAM-1 mediated leucocytes infiltration and inhibits tumor growth in vivo." (PMID 24742333, 2014). "In a model of colon carcinoma, tumor cell interaction with liver sinusoidal endothelium through ICAM-1 led to a cyclo-oxygenase 2-dependent IL-1 production, which upregulated the expression of mannose receptor on TECs and decreased anti-tumor activity of interacting lymphocytes." (PMID 24734218, 2014). "Although ICAM-1 expression was modulated following radiation exposure in vitro, it was not upregulated after radiation exposure in vivo, which suggests a role for the tumor microenvironment in ICAM-1 regulation, in agreement with other reports." (PMID 24480782, 2014).
tumor (continued). "Expression of ICAM-1 in tumor tissues was also studied by using immunohistochemistry method." (PMID 24742333, 2014). "One critical aspect of our study was to examine whether knockdown of E2F1 in DU145 cell-derived tumor tissues is able to increase expression of ICAM-1 and ICAM-1-mediated leucocytes infiltration in vivo." (PMID 24742333, 2014). "An overexpression of ET(B)R by TECs has been associated with a decreased ICAM-1 expression and an absence of tumor-infiltrating lymphocytes (TILs), and identified as a poor prognosis marker." (PMID 24734218, 2014). "A549/ICAM-1 cells were shown to induce in vitro cell invasion and in vivo tumor metastasis." (PMID 24901215, 2014). "Therefore, it is possible that this local tumour hyperthermia treatment also increases ICAM-1 on the tumour vasculature and enhances trafficking of T cells or other immune cells into the tumour." (PMID 25430985, 2014). "For example, IL-1β, a special form of IL-1, can stimulate expression of VEGF and TNFα to promote tumor angiogenesis and adhesion molecules, including intercellular-adhesion molecule 1 (ICAM-1), vascular cell adhesion molecule 1 (VCAM-1) and E-selectin, to enhance invasion." (PMID 24338768, 2014). "A very weak signal was observed in DU145/sh-ICAM-1 tumor tissues." (PMID 24742333, 2014). "Similarly, we found that doxorubicin treatment ex vivo significantly increased levels of ICAM-1 in the cytoplasm and membrane of tumor cells (p=0.023), which was prevented by MLN120B (p=0.008)." (PMID 24344116, 2014). "Next, we evaluated whether p65 and p50 nuclear translocation in doxorubicin-treated tumor specimens was associated with an increase in the expression of NF-κB target genes TNFAIP3, ICAM-1 and CXCL-1." (PMID 24344116, 2014). "However, high concentrations of soluble ICAM-1 (sICAM-1) were detected in malignant pleural fluid samples and A549 supernatants, implying that the level of sICAM-1 is high in the tumour microenvironment." (PMID 23565296, 2013). "Although studies of expression levels of CD86, MHC class I, and MHC class II are important to evaluate the activation levels of DCs in anti-tumor immune responses, other activation markers for DCs might exist, such as ICAM-1 or B7." (PMID 23865808, 2013). "Expression in U87-MG and U118 cell lines, PA-NAV, PA-GAS and PA-PET initial tumor specimen and in the excised tumor of the case report: we quantified the ICAM1, CRK, CD36, and IQGAP1 mRNA expression in our in vitro models and in the surgical specimen of the case report." (PMID 24252689, 2013). "To determine whether the tumour microenvironment was responsible for the accumulation of tumour-infiltrating DN NK cells, we measured the expression of ICAM-1, a ligand for CD11b/CD18 (also referred to as Mac-1 and CR3), on tumour cell lines." (PMID 23565296, 2013). "In addition, the high level of WISP-1 expression correlated strongly with ICAM-1 expression and tumor stage." (PMID 24205072, 2013). "Similarly, examination of tumor tissue removed from head and neck cancer patients following RT revealed marked increase in endothelial ICAM-1 expression, in concert with increased β2 integrin-positive myeloid cell infiltration." (PMID 23251903, 2012). "RT can upregulate expression of adhesion molecules, such as VCAM-1, E-selectin, and ICAM-1, by vascular endothelial cells within the tumor and induce expression of T cell chemokines that promote T cell adhesion and extravasation into the tumor microenvironment." (PMID 23087904, 2012). "Blockade of CD11b, the ligand for ICAM-1, in a transplantable murine squamous carcinoma model significantly reduced tumor-infiltration by CD11b+ myeloid cells following RT resulting in diminished tumor growth." (PMID 23251903, 2012). "The interaction between tumor cells and lymphocytes and endothelial cells via ICAM-1 is complex." (PMID 23300837, 2012).
tumor (continued). "Alterations in the oligosaccharide structure (glycan) of ICAM-1 may significantly influence cell proliferation, differentiation, adhesion, migration, tumor invasion and metastases." (PMID 23300837, 2012). "Moreover, understanding the underlying mechanisms and resolving the glycan structures produced upon ATRA induction will shed new light onto the functional versatility of ICAM-1 in tumor progression." (PMID 23300837, 2012). "Importantly, EBP1 downregulates MMP9 but enhances the protein levels of E-cadherin and another critical molecule, ICAM-1, which is involved in tumor immunity and metastasis." (PMID 23110497, 2012). "Additional NF-κB target genes which contribute tumor cell migration and/or metastasis include cellular adhesion molecular, such as ICAM-1 and VCAM-1; matrix metalloproteinases, such as MMP-9; chemokine receptors, such as CXCR4, and vascular endothelial growth factor (VEGF)." (PMID 22952718, 2012). "CD3ε, CD25, and ICAM-1 mRNA levels in tumor biopsies showed a significant correlation with histological tumor type (p = 0.003, p = 0.004, p = 0.03, respectively), with nodular tumor type having lower levels of gene expression than the superficial tumors or mixed tumors." (PMID 21980389, 2011). "ICAM-1 plays an important role in leukocyte migration from the capillary to the site of tissue damage, an ability that could be used equally well by the tumor cell to reach the circulation." (PMID 24212946, 2011). "ICAM-1 plays a role in promoting lymphocyte-mediated tumor killing, and this occurs as a result of enhanced binding of peripheral blood mononuclear cells to the tumor cells and subsequent tumor cell lysis." (PMID 19822019, 2009). "Our results suggest that tumor cell differentiation may be influenced by genetic variation in ICAM-1 in Chinese population." (PMID 19822019, 2009). "Although it is unclear how the ICAM-1 K469E polymorphism contributes to the pathogenesis of CRC, we found that the increase in ICAM-1 expression was accompanied by well-differentiation in tumor tissues of KK genotype patients." (PMID 19822019, 2009). "We next set out to assess whether the K469E genotype is correlated with differences in ICAM-1 expression using lysate extracted from the tumor and matched adjacent normal tissues of CRC patients with KK or KE+EE genotypes." (PMID 19822019, 2009). "Both sinusoidal cell types express and secrete ICAM-1 induced by tumor-derived factors." (PMID 18844982, 2008). "ICAM-1 acts in association with neutrophils by inducing polymorphonuclear (PMN) cell degranulation and releasing proteases, which break down the endothelial barrier and promote tumor cell migration during metastasis formation." (PMID 18958307, 2008). "In previous studies, we showed that heparin could successfully down-regulate ICAM-1 production in vitro resulting in preventing tumor adhesion." (PMID 19662219, 2007). "If fibrinogen were to bind to ICAM-1 on endothelial cells, it might promote stable adhesion of tumor cells to the endothelium of target organs." (PMID 16740157, 2006). "There was a significant association between patients whose tumours expressed ICAM-1 and survival (P= 0.03), suggesting that expression levels of ICAM-1 may have clinical relevance." (PMID 11720474, 2001). "Collectively, these data provide further evidence for ICAM-1 involvement in the tumour/LAK cell response and indicates that the RA-induced increase in mICAM-1 levels are partly responsible for the increase in susceptibility of the tumour cells." (PMID 10408388, 1999). "Immunohistochemical analysis of ICAM-1 in tumour cells was performed in 20 cases." (PMID 9514061, 1998). "Levels of ICAM-1 mRNA were also up-regulated by tumour-secreted IL-1alpha." (PMID 9374368, 1997). "Antisense ICAM-1 oligonucleotide inhibited lysis by NK cells of TNF-alpha-treated tumour cells." (PMID 7908214, 1994). "Moreover, EGF upregulates αMβ2 integrin on TAMs and ICAM-1 on tumor cells." (PMID 41280929, 2025).